ARID1A (AT-rich interaction domain 1A)
Diseases named in the same sentence as ARID1A in open-access papers (continued):
Sharing a sentence is not in itself a finding about the gene and the disease.
endometriosis (continued). "Prior research has suggested that the presence of ARID1A somatic mutation and subsequent absence of BAF250a protein do not demonstrate a correlation between endometriosis and the ovarian response to chemotherapy." (PMID 38384812, 2024). "The SWItch/Sucrose Non-Fermentable (SWI/SNF) complex and ARID1A gene alterations offer valuable insights into the pathogenesis of endometriosis and endometriosis-associated ovarian cancer." (PMID 39309679, 2024). "Additionally, somatic mutations in cancer driver genes ARID1A, PIK3CA, KRAS, and PPP2R1A are found in deep infiltrating endometriosis." (PMID 39309679, 2024). "Moreover, different types of gene-based biomarkers such as ARID1A, PIK3CA, KRAS and CTNNB1 are recurrently mutated in endometrial cancer type I, endometriosis and endometriosis-associated ovarian tumors." (PMID 37189525, 2023). "In fact, these have mutations in common with endometriosis, such as PTEN, PIK3CA, KRAS and ARID1A." (PMID 37189525, 2023). "This is reiterated by data showing the presence of molecular alterations such as ARID1A mutations typical of EAOC in contiguous atypical endometriosis but not in adjacent endometriotic lesions." (PMID 37799950, 2023). "ARID1A gene mutation and activation of PI3K/AKT pathway may be an initial change in endometriosis SCs, followed by gene modifications caused by ReTIAR syndrome and DNA damage resulting from oxidative stress and action of heme products." (PMID 36612107, 2022). "LtfCre0/+; (Gt)R26Pik3ca*H1047R; Arid1afl/fl mice (henceforth, PIK3CA/ARID1A mutant mice) develop endometrial hyperplasia and myometrial invasion with features of endometrioid carcinoma, which can also develop an endometriosis phenotype following uterotubal incision surgery." (PMID 36424602, 2022). "Recurrent mutations, such as KRAS, PIK3CA (phosphatidylinositol-4,5-bisphosphate 3-kinase), PPP2R1A (Protein Phosphatase 2 Scaffold Subunit Alpha), and ARID1A (AT-Rich Interaction Domain 1A), are observed in endometriosis and adenomyosis, which suggests similar disease development." (PMID 35206475, 2022). "Because ablation of Arid1a disrupts PGR signaling and ARID1A can directly bind to PRA, ARID1A is essential for normal endometrial functions and reduced ARID1A expression can alter PGR signaling leading to progesterone resistance in the endometrium with endometriosis." (PMID 35203298, 2022). "Inactivation or epigenetic silencing of the ARID1A gene in the epithelial component of endometriosis may result from chronic inflammation and cyclic regeneration." (PMID 36612107, 2022). "Consequently, our data unravelled that silencing HDAC2 increased HNF4A expression through inhibition of deacetylation to upregulate ARID1A, thus preventing endometriosis." (PMID 34586697, 2021). "HDAC2 was upregulated but HNF4A and ARID1A were downregulated in endometriosis tissues." (PMID 34586697, 2021). "Mutation of the ARID1A gene, which is mainly involved in the formation of the SWI/SNF chromatin complex, may be an early event in the transformation of endometriosis into cancer." (PMID 34150634, 2021). "In this context, we speculated that the network of HDAC2, HNF4A and ARID1A might be correlated with the pathogenesis of endometriosis." (PMID 34586697, 2021). "Therefore, this study was designed to explore the mechanism of HDAC2 orchestrating hepatocyte nuclear factor 4α/AT‐rich interactive domain 1A (HNF4A/ARID1A) axis in endometriosis." (PMID 34586697, 2021). "A previous study has reported that ARID1A is poorly expressed in endometriosis." (PMID 34586697, 2021). "Collectively, HDAC2 silencing might upregulate HNF4A via repression of deacetylation to activate ARID1A, thus preventing the occurrence of endometriosis." (PMID 34586697, 2021).
endometriosis (continued). "In summary, all 78 endometriosis samples retained ARID1A protein expression regardless of the ARID1A mutation status." (PMID 32868822, 2020). "Although several previous studies demonstrated that ARID1A was expressed in endometriosis by immunohistochemical analysis, the mutation status of ARID1A in endometriotic epithelial cells was not investigated." (PMID 32868822, 2020). "To clarify the significance of ARID1A loss-of-function mutations in endometriosis, we compared the clinicopathological features of ovarian endometriosis patients with ARID1A loss-of-function mutations to those without ARID1A mutations." (PMID 32868822, 2020). "We revealed that not only 70 endometriosis samples without ARID1A mutations but also eight endometriosis samples with ARID1A loss-of-function mutations retained ARID1A protein expression." (PMID 32868822, 2020). "Similarly, several studies showed that ARID1A was expressed in almost all benign endometriosis lesions if ARID1A protein expression in stromal cells was correctly assessed as an internal positive control." (PMID 32868822, 2020). "Because inactivating ARID1A mutations and the loss of BAF250a function have been identified in atypical endometriosis at the periphery of OCCC tumors, they are believed to be majorly involved in the development of OCCC from endometriosis." (PMID 31366141, 2019). "Similarly, anatomical subtypes of endometriosis, such as ovarian endometrioma (EN-OV) and deep infiltrating (EN-DI) endometriosis, harbor mutations in PIK3CA, ARID1A, PPP2R1A, and/or KRAS20,21." (PMID 31857578, 2019). "Similar deletion of ARID1A alone or with knock-in of Pik3ca mutations showed ovarian surface epithelium hyperplasia but no endometriosis." (PMID 30087267, 2018). "In addition, they added H2O2 to induce OS in cultured cells from patients affected by primary endometriosis and assessed possible alteration of ARID1A gene expression based on different H2O2 concentrations." (PMID 29743986, 2018). "In this case, the SMBT, clear cell tumor, and endometriosis samples showed no loss of expression and/or mutation of ARID1A." (PMID 26075120, 2015). "Within these cases, all atypical endometriosis and 86% of non-atypical endometriosis also lost ARID1A expression, suggesting that loss of ARID1A expression occurs as a very early event in the malignancy development." (PMID 23466883, 2013). "Mutations in the ARID1A gene have been noted in clear-cell tumours and contiguous atypical endometriosis, but not in distant endometriotic lesions." (PMID 22361336, 2012). "Whether ARID1A defects present an actionable target in endometriosis also remains to be determined, with the types of drugs discovered to treat malignancy needing to be considered in a different context for potential management of a predominantly benign chronic condition." (PMID 39272926, 2024). "Therefore, the synergistic action of ARID1A loss and PI3K/AKT/mTOR pathway upregulation in the malignant progression of endometriosis can be partially explained by their cooperation in activating IL-6 and thus in promoting a pro-tumorigenic inflammatory cytokine signaling." (PMID 37627318, 2023). "Therefore, new therapeutic strategies, such as ARID1A mutations, in OCCC might improve chemotherapy sensitivity, prolong survival, and even prevent malignancy from progressing from endometriosis to OCCC." (PMID 36873929, 2023). "Our cohort also showed the concomitant loss of ARID1A expression associated with PI3KCA mutation, as previously observed; those alterations are thought to occur at an early stage in the development of OCCC due to its presence in endometriosis precursor lesions." (PMID 37400764, 2023). "Interestingly, somatic driven mutations in KRAS, PTEN, PIK3CA and ARID1A have been also observed in more than 26% of cases of deep infiltrating endometriosis lesions, which are associated with virtually no risk of malignant transformation." (PMID 35457244, 2022).
endometriosis (continued). "In this context, the loss of ARID1A expression in atypical endometriosis might be an initial but not sufficient step in ovarian carcinogenesis, which starts after the second mutation event concerning the PI3K/AKT/PTEN pathway." (PMID 36612107, 2022). "Although we used serial sections to assess ARID1A mutations and ARID1A protein expression in endometriosis, we could not extract DNA, RNA and protein from the same tissue simultaneously." (PMID 32868822, 2020). "Altogether, the increased OS might have consequences in gene expression, rgarding the down-regulation of the tumour suppressor gene AT-rich interaction domain A (ARID1A) via promoter hypermethylation, which is considered an early event in endometriosis malignant transformation." (PMID 31731537, 2019). "Importantly, in some patients ARID1A mutations and loss of BAF250a protein have been observed in the tumor and the contiguous atypical endometriosis, but not in distant endometriotic lesions." (PMID 29389895, 2018). "ARID1A mutations and loss of BAF250a expression were both identified in the tumor and in the contiguous atypical endometriosis but could not be detected in distant endometriotic lesions." (PMID 29743986, 2018). "Moreover, ARID1A is believed to be involved in the pathogenesis of endometriosis." (PMID 30176911, 2018). "ARID1A regulates important cellular functions (proliferation and genomic stability) as a tumour suppressor gene; therefore, it was thought that it might play a role in the transformation of endometriosis to cancer." (PMID 29456620, 2018). "Moreover, atypical endometriosis and EAOC may share several molecular alterations such as ARID1A and PIK3CA mutations, PTEN loss, MET amplifications, and HNF1B overexpression, suggesting a common molecular mechanism for malignant development." (PMID 27992377, 2017). "Next-generation sequencing (NGS) has shown that endometriosis and adenomyosis involve genetic alterations such as KRAS, PIK3CA, PPP2R1A and ARID1A." (PMID 37296736, 2023). "Reactive oxygen species have been shown to induce increased methylation of the ARID1A promoter through the action of DNMT1, resulting in the suppression of ARID1A expression in conditions like endometriosis." (PMID 38041544, 2023). "Gene alterations found in both endometriosis and clear-cell ovarian carcinoma include genes such as PIK3CA, PTEN, ERBB2, KRAS, ARID1A, PPP2R1A, MLH1, and CTNNB1." (PMID 35563789, 2022). "Therefore, although the sequencing studies in non-atypical endometriosis are lacking, the IHC studies could serve as a good approximation of mutational ARID1A gene status." (PMID 36612107, 2022). "In the endometriosis group and groups with combination of autoimplantation and DMBA induction, the median percentage of ARID1A expression was lower compared to the sham group." (PMID 33639673, 2021). "Both ARID1A and HNF1B play a role in the pathogenesis of ovarian CCC arose in endometriosis and both were proposed as new experimental markers in EC." (PMID 25885815, 2015). "Notably, several studies report decreased levels of proteins such as LIF, ARID1A (AT-rich interaction domain 1A), and HNF4A (hepatocyte nuclear factor 4 alpha) in the endometriosis tissues." (PMID 40649777, 2025). "Based on this shared expression of ARID1A and the observed transcriptional similarities, we postulate that ovarian CCC cells may originate from these specific epithelial cells present in the endometriosis condition." (PMID 39149248, 2024). "Furthermore, ARID1A, a well-established oncogene in CCC, is highly expressed in these same endometriosis cells." (PMID 39149248, 2024). "In the same vein, in a series of ARID1A-deficient EAOC samples, all of the case-matched atypical endometriosis and 86% of the case-matched non-atypical endometriosis samples exhibited loss of ARID1A immunoreactivity." (PMID 37627318, 2023).
endometriosis (continued). "Interestingly, the TOV21G (ARID1A mutant), IGROV1 (ARID1A mutant), and ES2 (clear cell subtype, potentially endometriosis-related) cell lines had varying sensitivity to tolinapant single agent." (PMID 36831656, 2023). "Furthermore, ovarian endometrioid cancer shares similar gene alterations with endometriosis, including PIK3CA, PTEN, KRAS, and ARID1A." (PMID 35563789, 2022). "Subsequent studies using immunohistochemistry have shown that ARID1A expression is usually lost in endometriosis coexisting with CCC, corresponding to the ARID1A expression level in carcinoma, but that ARID1A expression is preserved in distal or benign endometriosis." (PMID 33809880, 2021). "ARID1A mutations are detected in adjacent endometriotic lesions of OCCC, but not in distant endometriosis in the same patient, indicating that OCCC arises from endometriosis, and that ARID1A functions as a major tumor suppressor during development of OCCC." (PMID 33917230, 2021). "In addition, ARID1A, a chromatin remodeling complex protein potentially regulated by SOX17, is decreased in endometrium from endometriosis patients." (PMID 31387263, 2019). "All 6 hESCs from women without endometriosis showed strong expression of ARID1A in hESCs from women without endometriosis." (PMID 26378916, 2015). "We observed the most abundant levels of ARID1A protein throughout the menstrual cycle in women without endometriosis." (PMID 26378916, 2015). "ARID1A protein levels were significantly lower in the eutopic endometrium of women with endometriosis compared to women without endometriosis." (PMID 26378916, 2015). "We found that ARID1A levels are remarkably lower in endometrium from women with endometriosis compared to women without endometriosis." (PMID 26378916, 2015). "To access ARID1A function in stroma cells, we examined the levels of ARID1A in human primary endometrial stromal cells (hESCs) from patients with or without endometriosis by Western blot." (PMID 26378916, 2015). "Taking this information into context, one can conclude that BAF250a loss in endometriosis could represent an EAOC precursor lesion; however, ARID1A mutations are neither a necessary driver mutation nor a significant determinant of the malignant phenotype." (PMID 29456620, 2018). "In the present study, we report that ARID1A protein levels are significantly lower in the eutopic endometrium of women with endometriosis compared to women without endometriosis, and mice with conditional ablation of Arid1a in PGR positive cells (Arid1ad/d) were sterile." (PMID 26378916, 2015). "However, the levels of ARID1A were significantly lower in both the stromal and epithelial cells of endometrium from proliferative and secretory phase endometriosis patients (n = 28) compared to women without endometriosis (n = 28)." (PMID 26378916, 2015). "ARID1A proteins were strongly detected in the stromal and epithelial cells of endometrium from the proliferative phase and early, mid, and late secretory phases in women without endometriosis (n = 7 per stage)." (PMID 26378916, 2015). "We showed attenuation of endometrial ARID1A in women with endometriosis as compared to women without endometriosis, and thus hypothesized that ARID1A plays an important role in ensuring normal fertility in the uterus." (PMID 26378916, 2015). "For example, some known somatic driver mutations in the genes ARID1A, PIK3CA, KRAS, and PPP2R1A have been found in the endometriotic lesions of 19 of 24 patients with deep-infiltrating endometriosis even though this form of endometriosis almost never undergoes malignant transformation." (PMID 29945886, 2018). "Interestingly, 5 of 6 hESCs from women with endometriosis did not detect ARID1A protein." (PMID 26378916, 2015). "Winarto and collaborators investigated tissue samples from patients with endometriosis, EAOC, or non-EAOC to observe that ARID1A expression decreases with increased OS a finding also corroborated in vitro." (PMID 31731537, 2019).
endometriosis (continued). "Furthermore, although PTEN knockout mice did not induce endometriosis carcinogenesis, endometriosis carcinogenesis was induced in 42% of PTEN and ARID1A double‐knockout mice." (PMID 41574315, 2026).
breast carcinoma (127 papers, 2012 to 2026). "Although our study establishes a compelling rationale for targeting ARID1B as a therapeutic vulnerability in ARID1A‐deficient breast cancers, further preclinical validation is warranted." (PMID 40671262, 2025). "In breast cancer, ARID1A loss-of-function leads to dysregulation of cell cycle checkpoints and impaired DNA repair and promotes epithelial-to-mesenchymal transition (EMT), jointly accelerating tumor proliferation and increasing therapeutic resistance." (PMID 41514650, 2025). "By explaining the mechanisms through which ARID1A mutations influence tumor behavior and immune interactions, researchers can address unique characteristics of both ER+ and ER- breast cancers, enhancing the precision of oncology and improving patient outcomes." (PMID 41514650, 2025). "Loss of ARID1A drives a luminal-to-basal lineage modification in ER+ breast cancer, which decreases ER- dependent transcription and resistance to endocrine therapies such as fulvestrant by separating SWI/SNF from ER/GATA3/FOXA1-bound enhancers." (PMID 41514650, 2025). "ARID1A protein levels were consistently low across many individual samples, aligning with its frequent loss and tumor suppressor role in breast cancer." (PMID 40671262, 2025). "AR shows context-dependent roles in ER breast cancers that loss of ARID1A disrupts chromatin regulators affecting drug sensitivities and self-regulation of ER; thus, future investigation of ARID1A-AR interactions across breast cancer subtypes is necessary." (PMID 41514650, 2025). "Using an epigenome-associated sgRNA library, they showed that ARID1A mutations lead to resistance to ER degraders as loss of ARID1A plays a key role in loss of luminal identity in ER + breast cancer cells." (PMID 40650785, 2025). "Together with this background, our objective is to investigate the crucial role of ARID1A, a key chromatin-remodeling gene whose alterations are increasingly linked to breast cancer and several other malignancies." (PMID 41514650, 2025). "Depletion of ARID1B also disrupts the stability of the SWI/SNF complex and inhibits the proliferation of ARID1A-deficient breast cancer." (PMID 38365747, 2024). "In vitro cell experiments have shown that ARID1A-deficient breast cancer cells have increased sensitivity to PI3K inhibitors (Buparlisib) and AKT inhibitors (MK-2206 and Perifosine)." (PMID 38427070, 2024). "According to data from the Cbioportal database, approximately 10% of all cancer cases and 7% of breast cancer cases exhibit ARID1A inactivation, including truncating mutations and deep depletion." (PMID 37173914, 2023). "In Her2-amplified breast cancer cell lines, ARID1A loss is associated with activation of the PI3K/AKT pathway, increased annexin A1 expression, and trastuzumab resistance." (PMID 38275587, 2023). "In breast cancer cells, ARID1A deficiency has been associated with enhanced migration, invasion and angiogenesis." (PMID 38041544, 2023). "Based on these findings, we suggest routine screening for variants in ARID1A along with BRCA1/2 in breast cancer patients from the Mexican-mestizo population." (PMID 37182128, 2023).